RNU6-379P (RNA, U6 small nuclear 379, pseudogene)
Gene: Small nuclear RNA gene on chromosome 22 (40,917,743 to 40,917,846, forward strand). Ensembl gene ENSG00000200683.
Homologues: Orthologues: chimpanzee U6 (99% identical), macaque U6 (96% identical), guinea pig U6 (89% identical), rabbit U6 (84% identical), mouse Gm22675 (81% identical). Paralogues in human: RNU6-1331P (91% identical), RNU6-41P (91% identical), RNU6-810P (91% identical), RNU6-97P (91% identical), RNU6-1011P (90% identical), RNU6-1019P (90% identical), RNU6-1122P (90% identical), RNU6-11P (90% identical), RNU6-1251P (90% identical), RNU6-189P (90% identical), RNU6-242P (90% identical), RNU6-263P (90% identical), and 1289 more.